LPCAT1 (lysophosphatidylcholine acyltransferase 1)
Diseases named in the same sentence as LPCAT1 in open-access papers (continued):
Sharing a sentence is not in itself a finding about the gene and the disease.
cancer (continued). "Emerging evidence showed that upregulation of LPCAT1 promotes cancer cell proliferation and metastasis while knocking down LPCAT1 could inhibit the growth of cancer cells by inducing cell cycle arrest at G0/G1 phase." (PMID 35615532, 2022). "Besides, upregulation of LPCAT1 has been reported in multiple cancers and links phospholipid changes to cancer cell proliferation and invasion ability." (PMID 34518524, 2021). "Additionally, LPCAT1 induces metastasis of cancer through complicated mechanisms, such as the lipid metabolism pathway and PI3K/ AKT/ MYC pathway." (PMID 34419067, 2021). "In addition, we used the ssGSEA algorithm to explore the correlation between LPCAT1 and cancer immune infiltrates." (PMID 34016103, 2021). "Additionally, we searched the THPA database to further examine the expressions of LPCAT1 in patients with various cancers." (PMID 30791942, 2019). "Among them, overexpression of the LPCAT1 gene may contribute to the progression and metastasis of human cancers, such as hepatocellular carcinoma, oral squamous cell carcinoma, breast cancer, prostate cancer, and colorectal cancer." (PMID 30845751, 2019). "LPCAT1 has been found to be a contributor to the progression, metastasis, and recurrence of cancer." (PMID 30791942, 2019). "The rate of LPCAT1 positivity may be higher in case of heterogeneity since we had only one 0.6 mm spot per cancer analyzed." (PMID 31533087, 2019). "Among the 150 ccRCC tissue spots included in the TMA, 147 (98.00%) spots were positive for LPCAT1 (staining in the membrane and cytoplasm of cancer cells), while only 4/30 (13.33%) normal renal tissue spots showed positive signals (staining in the renal tubular) (χ2 test, p < 0.001)." (PMID 28494778, 2017). "LPCAT1 level is highly elevated and may play a potential oncogenic role in multiple human cancers." (PMID 35880567, 2022). "Therefore, LPCAT1 seems to contribute to tumour growth and metastasis in these types of cancer." (PMID 29757226, 2018). "Moreover, recent studies suggest a correlation between LPCAT1 expression and cancer progression." (PMID 24646950, 2014). "A review of the literature on PC metabolism in various cancers revealed that FADS1, FASN, PCYT1A, LPCAT1, and PLD2 are involved in PC metabolism in multiple cancers." (PMID 40148316, 2025). "Compared with normal breast tissues, PIGR, GPLD1, PLA2G5 and CORO1A were down-regulated in cancer tissues, while EIF4EBP1 and LPCAT1 were significantly up-regulated." (PMID 41450825, 2025). "LPCAT1 overexpression boosts LPC to PC conversion, influencing cell proliferation and fluidity and promoting cancer growth and metastasis via membrane PC-level alterations." (PMID 38732512, 2024). "Knockdown studies have demonstrated the essential role of LPCAT1 in the proliferation, migration, invasion, epithelial–mesenchymal transition (EMT) of cancer cells, and overall tumor growth." (PMID 38893234, 2024). "Lpcat1 modulation can play an important role in cancer pathogenesis and progression and we found this enzyme also significantly upregulated in the mAITL and hAITL neoplastic Tfh cells which suggest that Lpcat1 inhibition might also be a possible novel treatment option." (PMID 38321568, 2024). "ACSL3, AIFM2, HSD17B7, LPCAT1, LSS, PLIN3 and RAB10 were up-regulated with the progression of cancer stage of HCC patients, while CIDEB, G0S2, HSD17B13, PLIN1 and PLIN2 were down-regulated." (PMID 37464334, 2023). "RAC1, BAX, EEF1E1, and LPCAT1, four highly interacted genes, showed differential expression at gene levels in HCC and played essential roles in cancer cells." (PMID 37999208, 2023). "The expression of LPCAT1, NDRG1, G6PD, CYP7A1, SPP1, SFN, and CDCA8 was significantly higher in cancer tissues than in paraneoplastic tissues, whereas the expression of DNASE1L3 was significantly lower in cancer tissues." (PMID 37717019, 2023).
cancer (continued). "In lung adenocarcinoma, LPCAT1 has been shown to activate the PI3K/AKT/MYC pathway, thereby promoting brain metastasis of cancer cells." (PMID 35880567, 2022). "Several publications have reported the relationships between these five ER-related genes (SPP1, KIF2C, LPCAT1, KPNA2, and FMO3) and cancers." (PMID 35915607, 2022). "Firstly, the expression level of LPCAT1 in eighteen types of cancers was evaluated in both TCGA and GEPIA databases, which found that the LPCAT1 expression was upregulated in LIHC." (PMID 35615532, 2022). "In conclusion, we identified LpCat1 was significantly over-expressed in HCC tissues and cancer cells." (PMID 34178664, 2021). "Among these, Lpcat1, a key enzyme of the Lands Cycle (an alternative pathway of PC synthesis) that converts LPC to PC, has been shown to play important roles in cancer pathogenesis and progression." (PMID 34202989, 2021). "Therefore, LPCAT1 could be a potential therapeutic target for cancer." (PMID 34518524, 2021). "LPCAT1 can enhance the proliferation and invasion of CRPC cells, while PAF is involved in the progression of many cancers via PAFR binding and signaling activation." (PMID 33137125, 2020). "In agreement with altered phosphatidylcholine (PC) metabolism in many types of cancer including CRC, overexpression of key enzymes of PC metabolism/remodelling, particularly CKα and LPCAT1, were found to correlate with cancer progression." (PMID 29358673, 2018). "Although further studies are needed to understand the interaction between LPCAT1 and the PAF/PAFR pathway and its functions in the cancer microenvironment, LPCAT1 is a potential biomarker of aggressive tumoral progression in human primary OSCCs." (PMID 25803864, 2015). "Because LPCAT1 has both LPLAT and lysoPAFAT activities, further studies are needed to determine which LPCAT1 products, disaturated glycerophospholipids or PAF, are involved in cancer progression." (PMID 24646950, 2014). "Lysophosphatidylcholine acyltransferase 1 (LPCAT1) is a cytosolic enzyme responsible for converting lysophosphatidylcholine to phosphatidylcholine and is found to be highly overexpressed in various cancers." (PMID 40733107, 2025). "LPCAT1 regulates cholesterol metabolism, promoting tumor progression through PI3K/EGFR signaling mediated activation of SREBP1, and suggesting that LPCAT1 is a key factor in cancer lipid synthesis." (PMID 41476608, 2025). "Lpcat1, a key enzyme of this cycle, that converts lysophosphatidylcholine (LPC) into PC was found upregulated in mAITL cells, and was already reported to play a role in cancer pathogenesis and progression." (PMID 38321568, 2024). "High-LPCAT1 expression could inhibit STAT1 expression, up-regulate CyclinD1, CyclinE, CDK4 and MMP-9, and decrease p27kip1 to promote cancer progression in HCC." (PMID 36307879, 2022). "High levels of LpCat1 in HCC could inhibit STAT1 expression, up-regulate CyclinD1, CyclinE, CDK4 and MMP-9, and decrease p27kip1 to promote cancer progression." (PMID 34178664, 2021). "In this study, we confirmed that LpCat1 was up-regulated in HCC tissues and cancer cell lines." (PMID 34178664, 2021). "In the subset of NST cancers the prognostic effect of LPCAT1 expression was independent of pT, and BRE grade (p<0.0001 each)." (PMID 31533087, 2019). "The mean Ki67LI increased from 23.5 ±1.2 for LPCAT1 negative cancers to 37.3 ±1.0 for cancers with strong LPCAT1 expression (p<0.0001)." (PMID 31533087, 2019). "Moreover, lysophosphatidylcholine acyltransferase 1 (LPCAT1), an enzyme involved in phospholipid metabolism, has been found to regulate the PI3K/AKT pathway by modulating the MYC transcription factor, thus enhancing cancer cell growth and metastasis." (PMID 40028322, 2025). "Furthermore, LPCAT1 expression was found to be positively correlated with the expression of exhausted T cells markers (CTL-4 and PD-1), which are key immune checkpoints used by cancer cells to help evade immune surveillance." (PMID 36307879, 2022).
cancer (continued). "Moreover, lysophosphatidylcholine acyltransferase 1 (LPCAT1), which converts lysoPCs into PCs is overexpressed in several cancers, and increased incorporation of PCs into cell membranes may facilitate proliferation, adhesion, and motility of cancer cells." (PMID 26817443, 2016). "Multivariate analysis for NST cancers including pT stage, nodal status, BRE grade and hormone receptors did not identify LPCAT1 expression as an independent prognosticator of survival." (PMID 31533087, 2019).
tumor (56 papers, 2013 to 2026). "A growing amount of evidence suggests that lipid metabolism, regulated by LPCAT1, is widely implicated in tumor progression." (PMID 35880567, 2022). "It was another aim of this study to analyze the association of LPCAT1 expression with tumor phenotype and prognosis of patients." (PMID 34148155, 2021). "Increased LPCAT1 staining was linked to undifferentiated tumor grading in both subtypes of EACs and ESCCs (p = 0.0273 and p = 0.0085)." (PMID 34148155, 2021). "Increased LPCAT1 expression was linked to undifferentiated tumor grading in both subtypes of EACs and ESCCs (p = 0.0273 and p = 0.0085)." (PMID 34148155, 2021). "Increased LPCAT1 expression was significantly linked to undifferentiated tumor grading in both subtypes of EACs and ESCCs." (PMID 34148155, 2021). "To explore the mechanism underlying the involvement of LPCAT1 in tumor metastasis, we set out to identify the relevant signaling pathways accounting for tumor growth inhibition caused by LPCAT1 knockdown." (PMID 30791942, 2019). "High levels of LPCAT1 immunostaining were significantly linked to unfavorable tumor features including high pT stage, high BRE grade, estrogen and progesterone receptor negativity, and HER2 amplification (p<0.0001 each)." (PMID 31533087, 2019). "In addition, the LPCAT1 level was significantly positively associated with tumor immune cell infiltration, biomarkers of immune cells, and immune checkpoint expression in LIHC." (PMID 35615532, 2022). "Functional assays demonstrated that LPCAT1 knockdown suppressed tumor cell proliferation, migration, and invasion while increasing cell death in vitro, and inhibited tumor growth in nude mouse xenograft models." (PMID 41792107, 2026). "In a xenograft tumor model, LPCAT1 overexpression increased tumor volume, elevated TC and FC levels, and upregulated LPCAT1, metastasis-related proteins, and cholesterol metabolism-related proteins, whereas shSOX2 exerted opposing effects." (PMID 41358198, 2025). "This limitation underscores the need for further analysis with improved resolution and detailed morphological annotation to more accurately identify the cellular contexts of LPCAT1 expression within the tumor microenvironment." (PMID 40723289, 2025). "In vivo, LPCAT1 enhanced tumor growth, lung metastasis, and cholesterol metabolism, while these effects were counteracted by SOX2 inhibition." (PMID 41358198, 2025). "We conducted qRT-PCR and Western blot assays on ccRCC samples to compare LPCAT1 expression between tumor and normal tissues." (PMID 39781455, 2025). "Immunoblotting of three representative pairs confirmed increased SOX2 and LPCAT1 protein in tumor relative to matched normal tissue, with GAPDH as loading control." (PMID 41358198, 2025). "The six‐gene diagnostic model (AIFM2, ABCG1, LIPG, DGAT2, LPCAT1, and VCP) demonstrated near‐perfect classification of tumor versus normal tissues (AUC ≈0.99 in ROC analysis; 99.8% accuracy in SVM analysis)." (PMID 40804485, 2025). "Our next step was to compare LPCAT1 gene expression levels between tumors and normal tissues using the GEO dataset GSE66272 and the TCGA-KIRC dataset, which showed significantly elevated LPCAT1 expression in tumor tissues." (PMID 39781455, 2025). "Tumor cells also manipulate phospholipid remodeling (LPCAT1) and lipid droplet formation (PLIN2) to evade immune detection and sustain growth under metabolic stress." (PMID 40076502, 2025). "Silencing LPCAT1 efficiently arrested tumor growth and inhibited malignant progression of BM in vivo without detectable toxicity." (PMID 38589859, 2024). "Gene silencing of LPCAT1 remarkably reduced tumor cell proliferation in vitro and attenuated BM in vivo." (PMID 38589859, 2024). "We therefore assessed the protein expression level of LPCAT1 using the Clinical Proteomic Tumor Analysis Consortium (CPTAC) database." (PMID 37662906, 2023).
tumor (continued). "The results of tissue samples showed that AGPAT5, LCLAT1, and LPCAT1 were significantly upregulated in HCC tumor tissues than in adjacent normal tissues." (PMID 36845084, 2023). "Accordingly, LPCAT1 has the potential as a therapeutic target for the inhibition of HCC progression as well as a marker for the prognosis of tumor patients." (PMID 36845084, 2023). "Immune cell infiltration of LPCAT1 in LIHC was finally investigated via Tumor Immune Estimation Resource (TIMER)." (PMID 35615532, 2022). "As the preceding results showed that LPCAT1-mediated gefitinib resistance of PC-9R cells is closely associated with the EGFR/PI3K/AKT pathway, we next verified this result by establishing a tumor-bearing mouse model." (PMID 35399731, 2022). "The remainder of the tumor mass was isolated either for qRT-PCR experiments to verify LPCAT1 expression, or for western blot analysis experiments to verify LPCAT1, Smad, p-Smad, ki-67, and SOX2 expressions." (PMID 35880567, 2022). "Several studies have shown that in many solid tumors chemoresistance, tumor aggressiveness and worsened survival correlated with LPCAT1." (PMID 35287685, 2022). "Several studies have shown that the conversion from LPC to PC, catalyzed by LPCAT1, is responsible for tumor progression." (PMID 35880567, 2022). "The tumor volumes of mice injected with pUbi-LPCAT1 HEC-1A cells were significantly greater than those in the pUbi-Ctrl group." (PMID 35880567, 2022). "In GC, lysophosphatidic acid is converted to phosphatidic acid with the help of lysophosphatidylcholine acyltransferase 1 (LPCAT1) which correlates with tumor depth and lymph node metastasis." (PMID 36618350, 2022). "We aim to explore the relationships between LPCAT1 expression and prognosis, clinicopathological features, tumor microenvironment (TME), immune cell infiltration, immune checkpoint gene expression, and related signaling pathways in HCC." (PMID 36307879, 2022). "Knockdown of LPCAT1 was able to reduce tumor growth in vivo, indicating that targeting LPCAT1 can be a promising strategy to treat or reduce tumor recurrence in amplified EGFRvIII GBMs." (PMID 35250970, 2022). "Of note, LPCAT1, an important enzyme of phospholipid metabolism, has attracted much attention from oncology researchers and is involved in carcinogenesis and tumor progression." (PMID 35399731, 2022). "We found that, in the xenograft model, LPCAT1 silencing resulted in tumor shrinkage and restored gefitinib sensitivity in the PC-9R cell line." (PMID 35399731, 2022). "As a result, our findings suggest that ncRNA-mediated upregulation of LPCAT1 correlates with poor outcomes and tumor immune infiltration in HCC patients." (PMID 35615532, 2022). "We applied the ssGSEA algorithm to further confirm the correlation of LPCAT1 expression and immune component by analysing the proportion of tumour infiltrating immune cells and constructing 28 sorts of immune cell profiles for the UCEC samples." (PMID 34016103, 2021). "Taken together, LPCAT1 reprograms tumor cell cholesterol metabolism in ESCC and can be used as a potential treatment target against ESCC." (PMID 34518524, 2021). "By using the ssGSEA algorithm, fifteen kinds of tumor-infiltrating cells (TICs) were found to be correlated with LPCAT1 expression." (PMID 34016103, 2021). "Tumor tissues and cancer cells with high LPCAT1 expression had increased PC and decreased LPC levels, and loss-of-function impaired cell growth and survival." (PMID 33413672, 2021). "Recently, LPCAT1 has been found to be overexpressed and to act as an oncogene in a variety of tumours." (PMID 34016103, 2021). "The discovery of an LPCAT1-TERT fusion transcript in ETT marks the first report of protein-coding LPCAT1-TERT fusion recurrence in any tumor type, with only four prior published reports of similar fusions occurring sporadically in other neoplasms." (PMID 34033669, 2021).